IL6 (interleukin 6)
Diseases named in the same sentence as IL6 in open-access papers (continued):
Sharing a sentence is not in itself a finding about the gene and the disease.
breast cancer (continued). "It is conceivable that BST2 is an important regulator in the STAT3/BST2/IL6 pathway leading to increased cell proliferation, as well as osteoclastic bone destruction and/or production in the bone metastatic breast cancer." (PMID 19338666, 2009). "IL-6 is an autocrine and paracrine growth factor for several cancers, including breast cancer and stimulates cancer cell growth and contributes to recurrence and metastasis in breast cancer." (PMID 19643025, 2009). "We showed here that MSC secreted IL-6 is key to the growth of the Skov-3 ovarian tumor model while we showed previously the importance of MSC-secreted EGF to the ERα-positive breast cancer model." (PMID 19352430, 2009). "This is consistent with in vitro studies in which the autocrine production of IL-6 in breast cancer cells was demonstrated to increase MDR expression within the tumor cells themselves." (PMID 18059400, 2008). "In this regard we are presently investigating the regulation of factors such as IL-6, IL-8 and IL-22 in breast cancer cells treated with IL-17." (PMID 19014637, 2008). "We treated MCF-10A cells with conditioned media from MDA-MB-231 breast cancer cells, which produce considerable levels of IL-6." (PMID 18939993, 2008). "Increased levels of IL-6 have been shown to increase breast cancer cells' resistance to doxorubicin." (PMID 18939993, 2008). "A growing body of evidence indicates a prominent and often contradictory role for IL-6 in breast cancer, and numerous reports have shown it to function in both a tumor-promoting and tumor-counteracting capacity." (PMID 18939993, 2008). "In summary, a principal mechanism of Stat3 activation in breast cancer is through the IL-6/gp130/Jak pathway." (PMID 17531096, 2007). "Increased serum levels of the cytokines IL-6, IL-8 and IL-10 have also been observed in patients suffering from breast cancer as compared with healthy women." (PMID 17261184, 2007). "Most cytokines were more abundant in breast carcinoma than in normal breast, with IL-6, IL-8, granulocyte CSF, IFN-γ, MCP-1 and MIP-1β being very abundant." (PMID 17261184, 2007). "The cytokines of the IL-1 family, IL-4 and its receptor, IL-6 and IL-10 are important candidate genes as they play an important role in breast cancer pathogenesis." (PMID 16842617, 2006). "The aim of this study was to evaluate any role of specific SNPs in the interleukin genes IL1A, IL1B, IL1RN, IL4R, IL6 and IL10 in predisposition to breast cancer susceptibility and severity." (PMID 16842617, 2006). "Circulating IL6 levels have been found to be higher in breast cancer patients compared to healthy controls and among those with breast cancer, correlate with the stage of the disease." (PMID 16842617, 2006). "By reducing basal and/or TNFα-induced IL-6 expression, ERα can reduce multidrug-resistant growth of breast cancer cells." (PMID 14970864, 2004). "Interleukin-6 has been shown to increase motility and confer multidrug resistance to breast cancer cells." (PMID 14970864, 2004). "It is noteworthy that, as in early-stage breast cancer, IL-6 functions as an inhibitor of cancer cell growth in benign prostate hyperplasia, but is correlated with a poor survival in stage-D prostate cancer." (PMID 12771987, 2003). "In breast cancer patients serum IL-6 has been shown to correlate with increasing numbers of involved sites, presence of liver metastasis, and disease progression." (PMID 11875705, 2002). "Plasma D-dimers, fibrinogen, IL-6, vascular endothelial growth factor and calculated vascular endothelial growth factor load in platelets are clearly increased in patients with breast cancer." (PMID 11875705, 2002).
breast cancer (continued). "It has been suggested that MPA decreases serum IL-6 levels and preserves the bodyweight of patients with advanced breast cancer." (PMID 10027341, 1999). "Though the majority of breast carcinomas expressed at least low levels of immunoreactive IL-6, we found that expression of this cytokine was inversely associated with histological tumour grade (P = 0.0017), but not with tumour size and nodal status." (PMID 10408869, 1999). "In contrast, IL-6, IL-1, and IL-33 can inhibit metastasis and mediate breast cancer cell death." (PMID 41596472, 2026). "IL-1, generated by immune cells such as macrophages and lymphocytes, is released downstream of oncogenes in breast cancer, triggering an inflammatory response by stimulating other pro-inflammatory cytokines such as IL-6, tumor necrosis factor (TNF), and IL-33 (an early warning cytokine)." (PMID 41596472, 2026). "In breast cancer, IL-6 promotes breast cancer cell viability, proliferation, and angiogenesis." (PMID 41491244, 2026). "In previous studies in breast cancer CTCs, over expression of IL-6 and IL-1β or both in CTC-associated neutrophils was sufficient to confer proliferative advantage to breast cancer cells upon dissemination, leading to faster metastasis development and shorter overall survival in mice." (PMID 41125825, 2026). "Interestingly, the same study reports an effect of FH on macrophage maturation, arginase, and IL6 production, consistent with our previously published research about the role of macrophages in the breast cancer microenvironment." (PMID 39378431, 2025). "JAK1 is essential for IL-6-class inflammatory cytokine signaling and plays a critical role in metastatic cancer progression in breast cancer and may provide a similar role in ovarian endometrioid carcinoma." (PMID 40981433, 2025). "Furthermore, IL-6 signaling has been proven to improve the survival of breast cancer stem-like cells (BCSCs), a subpopulation rich in TNBC naturally resistant to chemotherapy and perhaps also capable of avoiding immune responses." (PMID 40868199, 2025). "In addition to the autophagy-exosome regulatory network, IL-6 secretion is modulated by autophagy in breast cancer." (PMID 39893499, 2025). "A recent study found that M. globosa colonization in breast tissue promotes the production of IL-17A by breast cancer cells, modulates NF-κB activity, and increases the expression of IL-6 and cyclooxygenase-2 (COX-2), thereby stimulating the proliferation of mice BC cells." (PMID 41597595, 2025). "Furthermore, IL-6 produced during acute inflammation resulting from biopsy or chemotherapy contributes to the development of lung metastatic outgrowth of disseminated mammary tumour cells." (PMID 40739350, 2025). "Osm (Oncostatin M) is a member of the IL-6 cytokine family which has a role in proliferation of breast cancer cells and may play a role in post lactational regression of the mammary gland." (PMID 40925719, 2025). "Our observations thus far led us to hypothesise that compression on breast cancer cells leads to secretion of IL-6 cytokine in a similar biphasic trend to exert pro-metastatic function in autocrine and paracrine signalling." (PMID 40371393, 2025). "There are some genetic association studies conducted on Bangladeshi Breast cancer and cervical cancer population to evaluate susceptible single nucleotide polymorphisms of INSIG2, HLA-DRB1, GCNT1P5, IL1β, IL4R, IL6, FGFR2, CYP1A1, ESR1 genes and disease outcome." (PMID 40920780, 2025). "Additionally, higher levels of HSPB1 resulted in increased IL-6 secretion, further promoting the advancement of breast cancer." (PMID 39858015, 2025). "Indeed, a meta-analysis indicated that exercise in breast cancer survivors, as well as in healthy populations, significantly reduces IL-6 (weighted mean difference ≈ −0.55 pg/mL)." (PMID 41303335, 2025).
breast cancer (continued). "Notably, IL-6/STAT3 signaling can induce a cancer stem cell phenotype: IL-6 drives the expansion of breast cancer stem-like cells by upregulating stemness factors and maintaining an undifferentiated, therapy-resistant state." (PMID 41007766, 2025). "Collectively, circRNA-14,052 knockdown could inhibit the breast cancer progression in vitro via miR-214-3p/IKBKB/IL-6/JAK2/STAT3 axis." (PMID 41044672, 2025). "Interestingly, there are reports that bronchial epithelial cells can express IL-6, and that IL-6 can act as a paracrine growth in breast cancer cell lines, which can upregulate both the soluble IL-6R and membrane bound IL-6R." (PMID 41497628, 2025). "Therefore, the objective of this study was to evaluate the effects of ADSC-derived extracellular vesicles on MCF-7 breast cancer cells, with a focus on cell viability, migration, IL-6/STAT3 signaling, and cytoskeletal structure." (PMID 41514893, 2025). "Clinically, high IL-6 is a consistently adverse prognostic indicator in breast cancer." (PMID 41007766, 2025). "Listeria-MAGE-B is a vaccination that is primarily used to treat breast cancer by inhibiting IL-6." (PMID 40805190, 2025). "In conclusion, this study demonstrates that IL‐6 contributes to eribulin resistance in breast cancer and that targeting IL‐6 may represent a potential therapeutic strategy to overcome this resistance." (PMID 41189442, 2025). "Importantly, we also found that IL‐6 inhibition potentiated the antitumor effects of eribulin in drug‐resistant breast cancer models, highlighting a novel therapeutic strategy to overcome resistance." (PMID 41189442, 2025). "Similarly, IL-6 was identified as a mediator for cross-talk between bone marrow and cancer cells in breast cancer models." (PMID 40335453, 2025). "Neuroinflammatory and systemic inflammatory responses, particularly increases in pro-inflammatory cytokines (IL-6, IL-1β, TNF-α) and reductions in hippocampal BDNF, are consistently linked to breast cancer and chemotherapy-induced cognitive impairment in animal models." (PMID 41155372, 2025). "In conclusion, we found that circRNA-14,052 could promote the progression of breast cancer via the miR-214-3p/IKBKB/IL6/JAK/STAT3 axis." (PMID 41044672, 2025). "The use of IL-6 and TNF-alpha as prognostic biomarkers could enhance the personalization of treatment in breast cancer patients by tailoring it according to the risk associated with overall survival and potential therapeutic response." (PMID 40558287, 2025). "Additionally, upregulation of the IL-6/STAT3 pathway has been detected in ER + breast cancer resistant to CDK4/6i palbociclib, which mediates the upregulation of EMT and BCSCs pathways." (PMID 40949156, 2025). "Furthermore, in the MMTV-PyMT mouse model of breast cancer metastasis, IAV-induced proliferation of PyMT+ small lesions and formation of micro-metastases in the lungs was dampened by IL-6 deficiency." (PMID 40739350, 2025). "Notably, IL-6 overexpression promotes resistance to anti-HER2 therapy in HER2-positive breast cancer models." (PMID 40558287, 2025). "For instance, IL-6 plays a central role in inflammation, autoimmunity, cancer, and age-related pathologies, primarily via the IL-6/STAT3 signaling pathway, and elevated levels of TNF-α have been associated with breast cancer recurrence." (PMID 41155372, 2025). "Interestingly, survivors of breast cancer in both groups had similar increases in myokine levels, apart from a greater increase in IL-6 in favour of HIIT immediately post exercise." (PMID 40608178, 2025). "IL-6 from CAFs affects breast cancer cell invasiveness and contributes to apoptosis resistance." (PMID 40136652, 2025). "In addition, LDHB KO or treatment with LDH inhibitors in ER- breast cancer cells reduced their motile ability in part through reducing the expression of IL-6, IL-8, and MMP-2." (PMID 40507273, 2025).
breast cancer (continued). "Additionally, downregulation of IL-6 through the IL-17 signaling pathway would be expected to decrease cell proliferation in breast cancer." (PMID 40769056, 2025). "Blocking IL6R using an IL6R antibody reversed IL6-induced breast cancer metastasis." (PMID 40841364, 2025). "In addition, recent research has shown that postmenopausal women with breast cancer have an up-regulation of the inflammatory cytokine IL-6, suggesting that these cytokines are crucial for the inflammatory process in such a disease condition." (PMID 40584290, 2025). "Our previous work demonstrated that tumor exosomal miR-9 (targeting SOCS3) and miR-181a (targeting PIAS3) synergistically activate the JAK/STAT signaling pathway, driving MDSC expansion and suggesting novel intervention strategies for IL-6-driven breast cancer." (PMID 41281644, 2025). "Similarly, in breast cancer, IL‐6–mediated expansion of the cancer stem cell population contributes to trastuzumab resistance, and IL‐6 receptor blockade has been reported to reverse this phenotype." (PMID 41189442, 2025). "In female breast cancer, IL6 can mediate the interaction between the TME and tumor cells." (PMID 40841364, 2025). "An anti-cytokine treatment involving IL-6, IL-8, and IL-18 receptor inhibitors is likely to suppress the intra-tumoral immunosuppressive network regarding the triple-negative molecular subtype of breast cancer." (PMID 40584290, 2025). "Such complexity may explain the diverse biological outcomes attributed to IL-6 across different breast cancer models." (PMID 41514893, 2025). "A previous study reported that C15:0 could suppress IL-6-induced JAK2/STAT3 signaling in MCF-7/stem-like breast cancer cells." (PMID 40356914, 2025). "Furthermore, commensal bacteria (e.g. Helicobacter hepaticus) also promotes the occurrence and distant metastasis of breast cancer by influencing the anti-tumor immune functions of IL-6 and neutrophils in the tumor microenvironment." (PMID 39926112, 2024). "Surgical stress is able to elevate levels of IL-6 and IL-8 in a murine breast cancer model, which could in turn stimulate neutrophils." (PMID 38419052, 2024). "Moreover, IL-6 inhibited proliferation of prostate cancer cells, colorectal cancer cells, and mammary cancer cells; however, treatment protocols can alter the results." (PMID 38928185, 2024). "Additionally, Xueqiang Gao confirmed that IL-6 can promote epithelial mesenchymal transformation (EMT) in breast cancer patients." (PMID 38540708, 2024). "Finally, studies also suggest that metformin can inhibit several STAT3-related signaling pathways known to be involved in breast cancer, including IL-6/JAK2/STAT3 signaling." (PMID 38543182, 2024). "However, the introduction of a MyD88 inhibitor disrupted the signal transduction of the TLR3-MyD88-NF-κB (p65)-IL6-Cyclin D1 pathway, leading to reduced breast cancer cell proliferation." (PMID 38347830, 2024). "We evaluate the IL-6-induced invasion of breast cancer cells by Transwell assay." (PMID 39201674, 2024). "In addition, EIF4A3 promotes the formation of circSERPINE2 in breast cancer, which is shuttled to tumor-associated macrophages through exosomes and enhances the secretion of Interleukin-6, leading to increased proliferation and invasion of breast cancer cells." (PMID 39550559, 2024). "IL-6: Supports cancer cell proliferation and survival; also promotes osteoclast differentiation, which leads to bone resorption.IL-8: Enhances the invasiveness and migration of breast cancer cells.IL-11: Contributes to osteoclastogenesis and bone resorption." (PMID 39605887, 2024).
breast cancer (continued). "Interestingly, breast cancer cells and the recombinant IL-6 protein, both known to activate fibroblasts in vitro, downregulated DCN in BSFs." (PMID 38667295, 2024). "Similarly, in ovarian cancer, bladder cancer, glioblastoma and breast cancer, IL-6 and IL-10 secreted by CSCs converted TAMs to M2 phenotype." (PMID 38613794, 2024). "Activation of MYC and IL-6 has been widely reported in breast cancer progression." (PMID 38654350, 2024). "IL-6 exerts a tumor-suppression effect on cancer cells derived from mammalian breast cancer." (PMID 39684820, 2024). "Extracellular IL-6 induces malignant characteristics in ductal breast cancer stem/progenitor cells, while the overexpression of IL-8 promotes stemness, stromal traits, acquisition of resistance, and the recruitment of immunosuppressive cells that foster tumor growth in the tumor microenvironment." (PMID 38347830, 2024). "The IL-6 cytokine is upregulated in sera of breast cancer patients when compared to normal samples." (PMID 39768178, 2024). "CAFs induce growth and radioresistance of breast cancer cells via interleukin-6 (IL-6) secretion." (PMID 39759028, 2024). "FGF-2 coordinates with fibronectin to support breast cancer dormancy, but adding IL-6, IL-8, or transforming growth factor β1 (TGF-β1) to that system disrupts dormancy, providing evidence toward inflammation-stimulated reactivation from dormancy in bone marrow." (PMID 38457510, 2024). "This includes inhibiting TNF-α release and IL-4 release although the production of some mediators such as IL-6 in MCF7 breast cancer cells and splenocytes may be increased by kynurenic acid indicating qualitative differences between tissues." (PMID 39201726, 2024). "Inflammatory cytokines, including TNF-α, IL-6, and prostaglandin E2, may promote the development of breast cancer by promoting cell proliferation and cell cycle progression." (PMID 38273418, 2024). "In addition, IL-6 produced during acute inflammation resulting from biopsy or chemotherapy contributes to the development of lung metastatic outgrowth of disseminated mammary tumor cells 9,10." (PMID 38645169, 2024). "Additionally, iron contributes to chemoresistance through the local IL‐6 paracrine loop in breast cancer cells." (PMID 38140764, 2024). "Moreover, GSEA findings indicate that elevated CD74 expression is linked to the activation of a range of immune responses in breast cancer, including IFN-α and IFN-γ responses, and the IL6-JAK-STAT3 pathway." (PMID 38582956, 2024). "Both BaP and PCB exposures can result in perturbation of inflammation mediators, leading to an inflammation microenvironment (via TNF-α and NFκB leading to IL-6 upregulation) that facilitates and contributes to the migration and invasion of breast cancer cells." (PMID 39548533, 2024). "Therefore, enhancements of MCT-1, IL-6/IL-6R, CXCL7 and PD-L1 expression are risk factors for predicting breast cancer violence and unfavorable clinical outcomes." (PMID 38505617, 2024). "Elevated IL-6 could promote the progression of several tumors, including breast cancer, liver cancer, and GC." (PMID 39251966, 2024). "In particular, in in vivo experiments, the peptide enhanced the antitumor effect of DOX through the combination of IND, decreased IL‐6 expression, increased CRT and CD4 levels, attenuated tumor‐associated inflammation, and enhanced immunity, which effectively inhibited breast cancer growth." (PMID 39545088, 2024). "In order to promote a novel phenotype in normal fibroblasts, we predicted that breast cancer cells could be able to cause loss of Cav1 and increase of MCT4, as well as elevate IL-6 and TGFβ in nearby normal fibroblasts." (PMID 38361760, 2024). "Given their critical roles in immune regulation, tumor growth, metastasis, and bone remodeling, interleukins, such as IL-6, IL-8, IL-1β, and IL-11, have been useful in predicting the clinical stage and prognosis of patients with breast cancer which has metastasized to the bone." (PMID 39125732, 2024).